CYP2W1 (cytochrome P450 family 2 subfamily W member 1)
Description:
A cytochrome P450 monooxygenase that may play a role in retinoid and phospholipid metabolism. Catalyzes the hydroxylation of saturated carbon hydrogen bonds. Hydroxylates all trans-retinoic acid (atRA) to 4-hydroxyretinoate and may regulate atRA clearance. Other retinoids such as all-trans retinol and all-trans retinal are potential endogenous substrates. Catalyzes both epoxidation of double bonds and hydroxylation of carbon hydrogen bonds of the fatty acyl chain of 1-acylphospholipids/2-lysophospholipids. Can metabolize various lysophospholipids classes including lysophosphatidylcholines (LPCs), lysophosphatidylinositols (LPIs), lysophosphatidylserines (LPSs), lysophosphatidylglycerols (LPGs), lysophosphatidylethanolamines (LPEs) and lysophosphatidic acids (LPAs). Has low or no activity toward 2-acylphospholipids/1-lysophospholipids, diacylphospholipids and free fatty acids. May play a role in tumorigenesis by activating procarcinogens such as aflatoxin B1, polycyclic aromatic hydrocarbon dihydrodiols and aromatic amines. Mechanistically, uses molecular oxygen inserting one oxygen atom into a substrate, and reducing the second into a water molecule, with two electrons provided by NADPH via cytochrome P450 reductase (CPR; NADPH-ferrihemoprotein reductase).
Synonyms: FLJ20359; MGC34287
Tractability: Small molecule: it belongs to a druggable protein family. Antibody: UniProt places it where antibodies can reach, with high confidence; UniProt predicts a signal peptide or a membrane-spanning region; its Gene Ontology location is reachable by antibodies, with medium confidence. PROTAC: a small molecule that binds it is known.
Target class: Enzyme; Cytochrome P450 family 2; Cytochrome P450
Gene: Protein-coding gene on chromosome 7 (983,181 to 989,640, forward strand). Ensembl gene ENSG00000073067.
Subcellular location: Endoplasmic reticulum lumen; Cell membrane; Microsome membrane
Pathways (Reactome):
Metabolism: Miscellaneous substrates; Xenobiotics
Gene Ontology:
Molecular function: all-trans retinal binding; all-trans-retinol binding; retinoic acid 4-hydroxylase activity; retinoic acid binding; heme binding; monooxygenase activity; oxidoreductase activity, acting on paired donors, with incorporation or reduction of molecular oxygen, reduced flavin or flavoprotein as one donor, and incorporation of one atom of oxygen; iron ion binding; oxidoreductase activity, acting on paired donors, with incorporation or reduction of molecular oxygen
Biological process: aflatoxin metabolic process; phospholipid metabolic process; retinoic acid catabolic process; xenobiotic metabolic process; cytochrome metabolic process
Cellular component: cell surface; endoplasmic reticulum lumen; plasma membrane; cytoplasm; endoplasmic reticulum membrane
Genetic constraint (gnomAD): Loss-of-function variants: 51 observed, 34.56 expected, observed/expected ratio (o/e) 1.48, 90% interval 1.18 to 1.84. The synonymous counts are far from expectation, so gnomAD's model fits this gene poorly and the ratio says little. Missense variants: 746 observed, 593.4 expected, observed/expected ratio (o/e) 1.26, 90% interval 1.18 to 1.34. Synonymous variants: 383 observed, 284.26 expected, observed/expected ratio (o/e) 1.35, 90% interval 1.24 to 1.47.
Homologues: Orthologues: chimpanzee CYP2W1 (99% identical), macaque CYP2W1 (94% identical), dog CYP2W1 (83% identical), guinea pig CYP2W1 (80% identical), pig CYP2W1 (78% identical), mouse Cyp2w1 (78% identical), rat Cyp2w1 (76% identical). Paralogues in human: CYP2D6 (42% identical), CYP2F1 (39% identical), CYP2S1 (39% identical), CYP2J2 (38% identical), CYP2C8 (38% identical), CYP2R1 (38% identical), CYP2B6 (37% identical), CYP2C19 (37% identical), CYP2C18 (37% identical), CYP2E1 (37% identical), CYP2A13 (36% identical), CYP2C9 (36% identical), and 3 more.
Diseases named in the same sentence as CYP2W1 in open-access papers:
CYP2W1 is named in the same sentence as 28 diseases in open-access papers, as found by Europe PMC text mining. Sharing a sentence is not in itself a finding about the gene and the disease. The quoted sentences say what the papers report.
colon carcinoma (13 papers, 2013 to 2025). "Other studies in colon cancer demonstrated that high CYP2W1 was associated with poor survival in grade 2 and 3 colon cancers." (PMID 35902379, 2022). "CYP2W1 expression in colon carcinoma is a prognostic factor: high expression is associated with poor survival." (PMID 27598485, 2016). "While in colon cancer expression of CYP2W1 occurs in about 30% of cases and is known to be associated with a poor prognosis, in adrenocortical tumors we observed a high expression in both benign and malignant tumors." (PMID 25144458, 2014). "CYP2W1, selectively expressed in ~30–36% of colon tumors, is an independent prognostic factor in stage II-III disease, likely via activation of procarcinogens and altered drug metabolism." (PMID 41179292, 2025). "Tumor-specific expression of CYP2W1 was detected in approximately 30% of higher-grade colon cancers, while the expression of this enzyme was insignificant in normal colon tissues." (PMID 33659048, 2021). "We have shown, using both a cell culture model and a mouse xenograft model (CYP2W1-expressing human colon carcinoma cells), that duocarmycin (chloromethylindolines) prodrugs can be converted to cytotoxic products by CYP2W1." (PMID 27598485, 2016). "By contrast, the monoclonal CYPW1 antibody and our 852 antibody recognized positive controls and CYP2W1 in colon cancer and in ACC and gave just a few bands in the tissue blot." (PMID 27598485, 2016). "The developmental shift from hypomethylation to hypermethylation in the exon 1/intron 1 CpG island of human CYP2W1 correlates with the gene expression levels of CYP2W1 and is perfectly consistent with similar changes found in normal versus colon tumor tissues." (PMID 25844926, 2015). "We chose the exon 1/intron 1 region, demethylation of which was previously shown to correlate with the expression of CYP2W1 in colon tumors." (PMID 25844926, 2015). "CYP2W1 mRNA and/or protein are known to be highly expressed during foetal life and in some cancers, particularly colon cancer, but also adrenocortical, lung and gastric cancers." (PMID 25144458, 2014). "Interestingly, CYP2W1 is highly expressed in fetal tissues and some tumors, including colon cancer, and its expression correlates with more aggressive tumor phenotype and poor outcome." (PMID 32033200, 2020). "On the other hand, the effect of CYP2W1 SNPs is currently unclear and, contrary to what has been described for duocarmycin analogs in colon cancer cells, CYP2W1*6 may have a different catalytic capacity for mitotane metabolism." (PMID 32033200, 2020). "Human cytochome P450 2W1 (CYP2W1) enzyme is expressed in fetal colon and in colon tumors." (PMID 27598485, 2016). "However, an appropriate colon cancer cell model with a constitutive CYP2W1 expression suitable for the in vitro regulation studies has hitherto not been identified." (PMID 25844926, 2015). "In addition to its expression in colon cancer cells, the CYP2W1 mRNA has been reported in rat fetal colon and in murine embryonic pooled tissues, whereas no significant expression has been reported in adult tissues." (PMID 25844926, 2015). "Additionally, CYP2W1 was reported to metabolize high affinity exogenous indolines, especially chloromethylindolines, into cytotoxic metabolites that inhibit growth of human colon tumors in a mouse xenograft model." (PMID 33659048, 2021). "However, the extensive analyses of CYP2W1 regulation in colon cancer cells are missing." (PMID 25844926, 2015). "In conclusion we show the developmental expression of CYP2W1 in the GI tract, to a great extent mediated by epigenetic modifications, its specific location, and regulation by anticancer drugs which can be considered as an adjuvant therapy of colon cancer metastases and hepatic cancers in the future." (PMID 25844926, 2015).
colon carcinoma (continued). "Here, we could describe the CYP2W1 mRNA and protein levels of CYP2W1 in human fetal colon and in SI, and using the immunohistochemical analysis, show the regio-selective distribution of CYP2W1 in the crypt cells of embryonic human colon, reminiscent of the CYP2W1 expression in colon cancer cells." (PMID 25844926, 2015). "On the other hand, CYP2W1 displayed variable levels of expression in A253, Detroit-562, FaDu and OSC19 cells and CYP2W1-transfected SW480 colon cancer cells used as a positive control." (PMID 34556703, 2021). "CYP2W1 was found to be selectively expressed in colon cancer tissues, but not in healthy tissues making it a putative tumor-specific drug target." (PMID 36437415, 2023). "Lack of CYP2W1 protein expression in any normal adult tissue, including normal adrenal cortex, makes the enzyme a promising target for future colon cancer specific therapy." (PMID 27598485, 2016). "CYP2W1 has also been reported to be an independent prognostic marker in stage II and III colon cancers; however, no studies have reported its prognostic significance in breast cancer." (PMID 35902379, 2022).
colorectal cancer (7 papers, 2014 to 2022). A primary or metastatic malignant neoplasm that affects the colon or rectum. "CYP2S1 and CYP2W1 are also involved in the metabolism of 5F‐203 and GW‐610 in breast and colorectal cancer cells." (PMID 35902379, 2022). "CYP2W1 has been proposed as an attractive target for colorectal cancer (CRC) therapy by exploiting its ability to activate duocarmycin prodrugs to cytotoxic metabolites." (PMID 25844926, 2015). "Although activation of CYP2W1 by demethylation in colorectal cancer (CRC) has been confirmed, the precise mechanisms of epigenetic modifications of CYP2W1 gene remain unclear." (PMID 33659048, 2021). "Tumor-specific expression of CYP2W1 and its ability to activate multiple prodrugs to cytotoxic metabolites in mouse xenograft models of colorectal carcinoma (CRC) suggest that this enzyme may be an important target for CRC treatment." (PMID 33659048, 2021). "We have reported that cytochrome P450 2W1 (CYP2W1) is expressed in about 30% of colorectal carcinoma (CRC) samples and 50% of liver metastases of CRC, but not in normal (non-transformed) adult intestine." (PMID 27598485, 2016). "Thus, CYP2W1 remains an independent biomarker for stages II and III colorectal carcinoma patients, but not for breast carcinoma." (PMID 25526449, 2014).
breast carcinoma (5 papers, 2014 to 2025). "Low cytoplasmic CYP2S1 and nuclear CYP2W1 expression (p = 0.035), and high nuclear CYP2S1 and cytoplasmic CYP2W1 expression (p = 0.023), were significantly associated with adverse breast cancer specific survival in the total patient cohort." (PMID 35902379, 2022). "Low nuclear CYP2W1 was significantly associated with adverse breast cancer specific survival (p = 0.012), with significance also maintained in multivariate analysis (HR: 0.677; 95% CI: 0.510–0.898; p = 0.007)." (PMID 35902379, 2022). "High expression of nuclear CYP2S1 and of CYP2W1 (p = 0.006) was also significantly associated with adverse breast cancer specific survival (p = 0.006)." (PMID 35902379, 2022). "None of the combined groupings of cytoplasmic and nuclear CYP2S1 or CYP2W1 showed any significant associations in ER‐negative (p = 0.194) or ER‐positive breast cancers (p = 0.354) respectively." (PMID 35902379, 2022). "CYP2S1 and CYP2W1 are associated with patient survival in breast cancer and may be important prognostic biomarkers." (PMID 35902379, 2022). "CYP2W1 is induced by the AhR and ARNT pathway, as shown in experiments in which treatment of MDA-MB-468 and MCF7 breast cancer cells with AhR ligands such as 5F-203 and GW-610 increased expression of CYP2W1." (PMID 41020804, 2025). "A high expression of CYP2W1 in tumor tissue, particularly in breast cancer (overexpression ~230-fold) in comparison to normal mammary gland tissues, makes this CYP isoform an attractive anticancer drug target." (PMID 41020804, 2025). "mRNA expression of CYP2S1 and CYP2W1 was also assessed in the Molecular Taxonomy of Breast Cancer International Consortium (METABRIC) cohort." (PMID 35902379, 2022). "The mRNA expression of CYP2W1 is reportedly upregulated in breast cancer and influences response to neoadjuvant chemotherapy (NACT)." (PMID 35902379, 2022). "The aim of the study was to investigate the protein expression of CYP2S1 and CYP2W1 in a large independent cohort of breast cancer patient tumour samples by immunohistochemistry." (PMID 35902379, 2022). "Although the prognostic values of CYP2S1 and CYP2W1 have been studied in other cancers, such as colon, there is little information regarding the prognostic value of CYP2S1 and CYP2W1 in breast cancers." (PMID 35902379, 2022). "CYP2S1 and CYP2W1 mRNA expression was also evaluated in a separate cohort of patients, the Molecular Taxonomy of Breast Cancer International Consortium (METABRIC) cohort." (PMID 35902379, 2022). "Current literature supports the findings in the present study that low expression of cytoplasmic CYP2S1 and of nuclear CYP2W1 results in shorter survival of breast cancer patients, a trend which was maintained even in multivariate analysis." (PMID 35902379, 2022). "Future studies should assess larger patient cohorts to determine the clinical utility of using CYP2S1 and CYP2W1 as biomarkers, including examining their role in the hormonal and chemotherapeutic response of breast cancer patients." (PMID 35902379, 2022). "The presence of CYP2W1 in breast cancers inhibits metabolism of retinoid into retinoic acid, reducing its anti‐proliferative effect in tumours." (PMID 35902379, 2022). "The benzothiazole 5F203 (and analogue GW-610) was found to selectively induce the expression of CYP2S1 and CYP2W1 in isogenic breast cancer cells depleted for the isoforms." (PMID 33809117, 2021). "Previous unpublished study suggested CYP2W1 induction by imatinib in leukaemia cells (GEO dataset: GDS3044) and CYP2W1 was induced in breast cancer cells following the treatment with 5F-203 or GW-610." (PMID 25844926, 2015). "Therefore, it seems that demethylation is a prerequisite for CYP2W1 expression, probably also in breast cancer cells." (PMID 41020804, 2025). "Similarly to CYP2S1, the expression of CYP2W1 was described in breast cancer cells differing in hormone receptor status, and its upregulation was found in breast cancer samples." (PMID 41020804, 2025).
breast carcinoma (continued). "Furthermore, studies have shown an increase in the transcript levels of CYP2W1 in responders to NACT compared to breast cancer patients with a stable or a progressive disease." (PMID 35902379, 2022). "The orphan CYPs, CYP2S1, and CYP2W1 are reportedly upregulated in breast cancer." (PMID 35902379, 2022). "Low nuclear, but not cytoplasmic, expression of CYP2W1 was also significantly associated with adverse breast cancer specific survival (p = 0.012)." (PMID 35902379, 2022). "In addition to looking at single marker expression, combined expression of both CYPs (CYP2S1 and CYP2W1) was also examined to assess the effects of marker combinations on breast cancer specific survival." (PMID 35902379, 2022). "In the molecular taxonomy of breast cancer international consortium (METABRIC) cohort, high CYP2S1 mRNA was significantly associated with basal like breast cancers compared to CYP2W1 which was predominantly expressed in luminal A tumours (SM and RA unpublished data)." (PMID 33809117, 2021). "In the most extensively investigated ER(+) MCF7 breast cancer cell line, the expression of three orphan CYPs, namely CYP4Z1, CYP2S1, and CYP2W1, was confirmed by several authors." (PMID 41020804, 2025). "A specific antibody, derived from the peptide sequence of CYP2W1, has already been developed and tested in MCF7 breast cancer cells." (PMID 41020804, 2025). "The others, such as CYP2W1, CYP2S1, CYP2U1, CYP4X1, and CYP4V2, are less specific, but their overexpression in breast cancer has also been found." (PMID 41020804, 2025). "In some smaller pools of patients, increased transcript levels of CYP2S1, CYP2W1, and CYP4F11 were found in breast cancer, adjacent, and normal breast cells." (PMID 41020804, 2025).
Adrenocortical Carcinoma (4 papers, 2014 to 2022). "To clarify this inconsistency, we have used qRT-PCR and Western blotting with CYP2W1-specific antibodies to probe a panel of 27 adrenocortical carcinomas and 35 normal adrenal cortex samples." (PMID 27598485, 2016). "Relationship between CYP2W1 immunoreactivity and baseline clinical or pathological characteristics of patients with adrenocortical carcinoma (only tumour samples derived from primary surgery, n = 196)." (PMID 25144458, 2014). "Relationship between CYP2W1 immunoreactivity and clinical outcome of patients with adrenocortical carcinoma treated with mitotane only (n = 72)." (PMID 25144458, 2014). "However, significant CYP2W1 protein expression was found in only one tumor sample (a testosterone-producing adrenocortical carcinoma) and not in any normal tissue." (PMID 27598485, 2016). "In total, 239 ACCs were analyzed using CYP2W1 immunohistochemistry and the results compared with those from adrenocortical adenomas, normal adrenals, other normal non-adrenal tissues, and several non-adrenocortical cancer forms." (PMID 27598485, 2016).
hepatocellular carcinoma (3 papers, 2015 to 2025). A malignant tumor that arises from hepatocytes. "Clinically, CYP2W1 upregulation has been associated with tumor aggressiveness, including higher metastatic potential, advanced histological differentiation, and advanced tumor stage, making it a potential biomarker for poor prognosis in colorectal cancer and hepatocellular carcinoma." (PMID 40136335, 2025). "The HCC2998 cells express similar or even higher amounts of CYP2W1 than HepG2 cells, a hepatoma cell line with constitutive expression of CYP2W1." (PMID 25844926, 2015). "Interestingly, recent studies have documented the reactivation of CYP2W1 expression in different cancers of epithelial origin such as the colon, colorectal, adrenal gland, breast, and hepatocellular carcinoma, with prevalence rates ranging from 30% to 60%." (PMID 40136335, 2025).
adrenal gland tumors (2 papers, 2014 to 2016). "CYP2W1 is mainly expressed in colorectal, hepatic and adrenal gland tumors, but it is rarely detected in normal tissues." (PMID 27367670, 2016). "Expression of CYP2W1 mRNA has been reported previously in a small number of adrenal tumors, but no details of the respective tumor entities were reported." (PMID 25144458, 2014).
hepatic cancers (2 papers, 2015 to 2021). "In both colon and liver cancers the prognosis of survival is worse in patients carrying tumors with higher levels of CYP2W1 expression." (PMID 25844926, 2015). "Furthermore, CYP2W1 can be used as an independent prognostic biomarker in liver cancer, and CYP17A1 can be used as a molecular marker in the diagnosis of liver cancer." (PMID 35003516, 2021).
adenoma (1 paper, 2014). A neoplasm arising from the epithelium. "This large study on CYP2W1 expression in adrenal glands reveals several key findings: we observed a high expression of CYP2W1 in the majority of adrenocortical tumors, comprising both adenomas and carcinomas, but also in normal adult adrenal tissue." (PMID 25144458, 2014).